HGF (hepatocyte growth factor)
Diseases named in the same sentence as HGF in open-access papers (continued):
Sharing a sentence is not in itself a finding about the gene and the disease.
Stroke (continued). "In the unstimulated saliva of stroke patients, we demonstrated significantly higher levels of chemotactic factors (CTACK/CCL27, IL-8/CXCL8, MIG/CXCL9, MIF) and growth factors (basic FGF, G-CSF, HGF, LIF, VEGF) compared to controls." (PMID 40221607, 2025). "Moreover, thrombin preconditioning of MSCs remarkably enriched their cargo contents, such as angiogenin, hepatocyte growth factor, vascular endothelial growth factor and BDNF, which are known to alleviate brain damage after stroke, compared to naïve MSCs." (PMID 35457266, 2022). "Injection of human HGF gene with a hemagglutinising virus into rat CSF after MCAO, reduced neurological deficit within 24 hours of treatment and increased the number of microvessels in stroke-affected tissue." (PMID 19292924, 2009). "Salivary basic FGF, HGF, IL-3 and LIF could serve as potential biomarkers for stroke." (PMID 40221607, 2025). "Ischaemic stroke patients had elevated plasma levels of HGF and SDF-1α, and lower IL-4 levels, compared to spontaneous cervical artery dissection patients without stroke." (PMID 38802464, 2024). "Three inflammatory markers (HGF, IL-8, and MIP-1a) were found to be elevated in patients with fatigue after stroke compared with the group without fatigue." (PMID 36756348, 2022). "The anti-inflammatory cytokines most correlated to negative GCS at 5–7 days post stroke include IGF-1 (p = 0.022, r = −0.409), HGF (p = 0.031, r = −0.388), and EGF (p = 0.033, r = −0.384)." (PMID 34360613, 2021). "Three genes (HGF, SNTB1, and SERPINC1 [MIM: 107300]) were found in the “stroke” group but not in the “long survivor” group." (PMID 32898326, 2020).
Insulin resistance (36 papers, 2006 to 2025). Increased resistance towards insulin, that is, diminished effectiveness of insulin in reducing blood glucose levels. "This increase in serum HGF levels is significantly associated with the development of insulin resistance." (PMID 35813634, 2022). "HGF increased beta cell mass in a dose-dependent manner; blocking HGF shuts down the compensatory mechanisms; and increases in HGF levels preceded the compensatory response associated with insulin resistance." (PMID 27158627, 2015). "In humans, higher serum HGF concentrations were associated with both newly diagnosed and long-standing Type 1 diabetes, insulin resistance, and prevalent Type 2 diabetes." (PMID 27158627, 2015). "HGF is positively associated with BMI and insulin resistance, and decreases after weight loss." (PMID 35980018, 2022). "The association between insulin resistance and HGF levels was supported by two additional prospective studies, suggesting that insulin and HGF resistance might converge." (PMID 35269415, 2022). "The current observation of a strong inverse association between plasma water T2 and HGF is consistent with this finding, as low water T2 detects early metabolic conditions thought to lead to type 2 diabetes, namely insulin resistance, subclinical inflammation and dyslipidemia." (PMID 30237882, 2018). "In the past 4 years a novel pathway involving a neural relay and two hormones – betatrophin and hepatocyte growth factor (HGF) – were implicated as an inter-organ communication system associated to the compensatory response of β cells in face of insulin-resistance." (PMID 24133484, 2013). "HGF binds to its receptor c-Met to activate pathways such as phosphoinositide 3-kinase–protein kinase B, thereby alleviating insulin resistance, enhancing glucose homeostasis, promoting angiogenesis, and inhibiting fibrosis." (PMID 41356597, 2025). "In type 2 DM, the HGF-Met system improves insulin sensitivity in mouse models of insulin resistance, likely through direct interactions between the Met receptor and the insulin receptor, affecting hepatic glucose management." (PMID 38654922, 2024). "HGF is pivotal in compensatory mechanisms for insulin resistance, correlating with β-cell mass increases and improved insulin signaling." (PMID 39063072, 2024). "HGF is considered an important component of the pathophysiology of insulin resistance, regulating the metabolic flux of glucose in different insulin-sensitive cell types and playing a role in β-cell homeostasis." (PMID 37170115, 2023). "Growing evidence points to a special interest of the HGF/MET axis in the crosstalk with insulin resistance and obesity-related molecular signatures." (PMID 35269415, 2022). "Elevated serum HGF level is significantly associated with the incidence of type 2 diabetes (T2DM) and the development of insulin resistance (IR)." (PMID 36726458, 2022). "A study that evaluates the links between HGF and insulin resistance highlights the beneficial effects of HGF in subjects with metabolic syndrome." (PMID 34829612, 2021). "In fact, a potential therapeutic role for HGF treatment for insulin resistance in type 2 diabetes has been suggested." (PMID 29484150, 2018). "All together, these data indicate that the HGF as one of the systemic gWAT, SM, and liver-derived growth factor plays a role in compensatory mechanism against insulin-resistance through the at least anti-inflammatory effect in adipose tissue." (PMID 28273932, 2017). "In the present study, using HGF-Tg mice and anti-HGF neutralizing antibody (HGF-Ab), we explored the role of HGF in obese and insulin resistance induced by HFD." (PMID 28273932, 2017). "While body weight in wild-type mice fed with high fat diet (HFD) for 14 weeks was significantly increased accompanied with insulin resistance, HGF-Tg mice prevented body weight gain and insulin resistance." (PMID 28273932, 2017).
Insulin resistance (continued). "Overall, our gain-of-function study using HGF-Tg mice and loss-of-function study using anti-HGF antibody revealed that HGF prevented HFD-induced obese and systemic insulin resistance by inhibiting the inflammatory response in adipose tissue in mice." (PMID 28273932, 2017). "For instance, the PPAR gamma agonists pioglitazone, irbesartan and telmisartan often used to treat patients with insulin resistance bind to and stimulate the HGF promoter to increase its expression in several organs." (PMID 28273932, 2017). "Twenty-four weeks of ezetimibe treatment ameliorated not only atherogenic lipid profiles but also anthropometric factors, insulin resistance and biomarkers such as HGF." (PMID 25575766, 2015). "Overall evidence from previous studies indicate that HGF level increases in metabolic syndrome and that HGF plays a role in insulin resistance and the development of T2DM." (PMID 27158627, 2015). "In conclusion, ezetimibe ameliorated not only atherogenic lipid profiles but also anthropometric factors, insulin resistance and biomarkers such as HGF." (PMID 25575766, 2015). "Similarly, HGF has been proposed as a therapeutic target for insulin resistance, promoting β-cell hyperplasia and hyperinsulinemia." (PMID 38654922, 2024). "Our analysis showed that some of the pathways activated predominantly at the 4 h time point in HG conditions have direct roles in mediating blood glucose homeostasis and have been implicated in insulin resistance, particularly PAK1, HGF, BMP and IGF-1 signaling pathways." (PMID 36463298, 2022). "In particular, HGF has been proposed as an important component of the pathophysiology of insulin resistance-related diseases since both HGF synthesis and secretion are upregulated in insulin resistance conditions." (PMID 35269415, 2022). "Indeed, in a physiological state, insulin suppresses lipolysis in adipose tissue, but through adaptive insulin resistance HGF/VEGF expression can decrease the suppressive action of insulin on lipolysis and thus increase fatty acid plasma concentration." (PMID 36497083, 2022). "Given that HGF significantly increases glucose metabolism and transport to myocytes and adipocytes, HGF could be used as a therapeutic target in the treatment of insulin resistance." (PMID 34829612, 2021). "In addition, cardiac-specific overexpression of HGF resulting in a fourfold increase in circulating HGF levels is sufficient to protect mice from high-fat diet-induced body weight gain and insulin resistance." (PMID 32372975, 2020). "Finally, HGF has a key role in insulin resistance, mechanism central to NAFLD onset and progression." (PMID 31547124, 2019). "Another important perspective from this study is that certain pharmaceutical strategies that target insulin resistance could enhance HGF expression in adipose tissue, arteries, and skeletal muscle." (PMID 28273932, 2017). "Furthermore, HGF exerts anti-oxidative properties by inducing glutathione and related enzymes and dampens insulin resistance and liver triglyceride and cholesterol content which might involve nuclear receptors such as the Farnesoid X receptor (FXR)." (PMID 35087852, 2021). "Moreover, HGF in circulation is positively correlated with the mass of perivascular fat, waist circumference, body mass index, body fat content and the development of insulin resistance." (PMID 32372975, 2020). "While HGF/MET can improve the metabolic profile of T2D, it conversely induces insulin resistance." (PMID 35269415, 2022). "Nevertheless, if we look at insulin resistance (or impaired glucose tolerance) not as a pathological status, but as a physiological adaptation to alimentary conditions, we may suggest that changes in glucose tolerance induced by HGF/VEGF GT reflect enhancement of energy supply for tissue recovery." (PMID 36497083, 2022).
endometriosis (34 papers, 2008 to 2025). The growth of functional endometrial tissue in anatomic sites outside the uterine body. "The association between HGF and endometriosis has been described in numerous studies, promoting cell proliferation and angiogenesis, two central characteristics of endometriotic lesions." (PMID 36902452, 2023). "Enhanced production of HGF by peritoneal macrophages in endometriosis (which is often associated with the hyperestrogenism-induced M2 shift in macrophage polarization) was demonstrated in several studies." (PMID 33672970, 2021). "The immunohistochemical analysis focused on the expression of IFN-τ, FGF-7, FGF-10, FGF-23, and HGF in both normal endometrial tissues and deep endometriosis samples." (PMID 40076699, 2025). "The findings demonstrated that FGF-7, FGF-10, and HGF exhibited significantly higher expression levels in the epithelium and stroma of normal controls compared to endometriosis samples." (PMID 40076699, 2025). "The hepatocyte growth factor promotes cell invasion, metastasis, and proliferation, a pivotal finding in endometriosis progression." (PMID 39683382, 2024). "While HGF (hepatocyte growth factor) are overexpressed in the peritoneal fluid of women with endometriosis, and it can effectively inhibit PGF-2α which induces uterine contraction, leads to vessel relaxation and thus improves blood flow and reduces ischemia." (PMID 37107282, 2023). "1,25(OH)2D3 treatment reduced HGF gene expression in the PFMCs of endometriosis patients at 24 and 48 h (p < 0.05 and <0.01, respectively)." (PMID 36259314, 2022). "As an estrogen-regulated factor, hepatocyte growth factor (HGF) exhibits multiple functions in endometriosis, a disease commonly believed to arise from the functionalis endometrium." (PMID 35887822, 2022). "It is widely accepted that HGF and its receptor c-Met are involved in the transformation of the epithelium and mesenchyme; however, most of these reports are about tumors or endometriosis." (PMID 35422866, 2022). "But regarding HGF, the peritoneum and endometriotic stromal cells seem to be primary production sources of this cytokine in endometriosis." (PMID 36259314, 2022). "Inflammatory cytokines such as IL‐6, LPS, and prostaglandins known as HGF inducers stimulate HGF production in the pelvic cavity of patients with endometriosis." (PMID 36259314, 2022). "Peritoneal cytokine profile in infertile patients with endometriosis was related to increased levels of stem cell growth factor b, hepatocyte growth factor (HGF), monocyte chemoattractant protein 1 (MCP-1) and IL-8, while IL-13 decreased significantly." (PMID 34449536, 2021). "The results showed that the level of HGF was significantly higher in the serum and PF in women with endometriosis than in controls (P < 0.001 and P < 0.05, respectively) (Figs. 2Aa and Ab)." (PMID 34930225, 2021). "Early and active endometriosis lesions in the peritoneum consist of abundant macrophages that correlate with HGF expressions." (PMID 33980258, 2021). "Other studies have also proven that the proliferation of ESCs and macrophages in patients with endometriosis in response to HGF in the culture medium had a more significant increase than the control group." (PMID 34930225, 2021). "According to other studies, it was revealed that HGF expression and c-Met in eutopic endometrium in patients with endometriosis increased compared to controls." (PMID 34930225, 2021). "We observed higher concentrations of HGF in serum and PF of patients with endometriosis compared to controls, and its concentrations were higher at the late stages of endometriosis." (PMID 34930225, 2021). "So far, few studies have been conducted regarding the production of HGF by PFMCs and PBMCs in patients with endometriosis, and some available studies have demonstrated the release of HGF by ESCs of endometriosis patients." (PMID 34930225, 2021).
endometriosis (continued). "Lipopolysaccharides (LPS), inflammatory cytokines, and prostaglandins stimulate HGF production in pelvic cavity of endometriotic patients and the peritoneum and endometriotic stromal cells seem to be primary sources of HGF in endometriosis." (PMID 31906916, 2020). "Some investigations further reveal a constant secretion of hepatocyte growth factor (HGF) from peritoneal macrophages in response to estrogen in endometriosis." (PMID 30518376, 2018). "Endometriosis patients show elevated levels of different pro-angiogenic factors including IL-8, IL-6, angiogenin, HGF and prostaglandin E2." (PMID 27695098, 2016). "Furthermore, IGF-1 and HGF levels are higher in peritoneal fluid of women with endometriosis compared with the healthy women." (PMID 35207581, 2022). "HGF, also known as the scatter factor, is an important growth factor related to endometriosis." (PMID 36259314, 2022). "Besides, based on a recent study, HGF can be used as the biomarkers for diagnosing endometriosis and predicting its prognosis." (PMID 36259314, 2022). "Studies have reported that HGF levels in the PF are elevated in women with endometriosis." (PMID 35740424, 2022). "Additionally, there was a significantly higher difference in the serum concentration of HGF in women at the stages III-IV of endometriosis compared to the patients with the stages I-II of the disease (P < 0.01)." (PMID 34930225, 2021). "Studies in women with endometriosis showed that hepatocyte growth factor (HGF) could also affect monocytes and macrophages and enhance inflammation." (PMID 34930225, 2021). "Hepatocyte growth factor (HGF) also plays a role in the development of endometriosis." (PMID 33980258, 2021). "Regarding the malignancy-like nature of endometriosis and the high concentration of HGF in the PF of patients with endometriosis, it is reasonable to speculate that HGF can play a role in the pathogenesis and progression of the endometriosis." (PMID 34930225, 2021). "Our current study showed that PFMCs in women with endometriosis could produce HGF considerably more than controls, and EESCs expressed substantially high levels of HGF than EuESCs and CESCs." (PMID 34930225, 2021). "Moreover, a recent study revealed that resveratrol treatment reduced expression of IGF-1 and HGF, pivotal molecules in endometriotic lesion growth and angiogenesis, in eutopic and ectopic endometrial stromal cells derived from endometriosis patients." (PMID 33919512, 2021). "The enhanced capacity of ESCs and macrophages proliferation may reflect more co-expression between HGF and its receptor in the cells of endometriosis patients." (PMID 34930225, 2021). "Therefore, therapies that disrupt HGF/c-MET signaling could be considered for further investigation in endometriosis patients, with the aim of retarding or halting disease progression." (PMID 40076450, 2025). "However, given the stemness activation and clonal expansion activity of IGF2 and the clonogenicity activity of HGF in FF, we predict that ovulation would facilitate both the initiation and progression of endometriosis and we are currently conducting animal studies to prove this." (PMID 35740424, 2022). "HGF and IGF-1 have several physiological and pathological effects that could contribute to the survival, proliferation, and invasion of endometrial stromal cells (ESCs) associated with endometriosis." (PMID 34930225, 2021). "So these findings imply that HGF may play a role in the pathogenesis of endometriosis." (PMID 31906916, 2020). "Another study demonstrated that estrogen stimulated PF macrophages to produce hepatocyte growth factor (HGF) and VEGF by ER, and HGF has a synergistic effect with E2 in the pathogenesis of endometriosis." (PMID 36865552, 2023). "In this study, 1,25(OH)2D3 treatment significantly reduced the protein expression of MCP‐1, HGF, and IGF‐1 in PBMCs and PFMC of endometriosis patients at 48 h." (PMID 36259314, 2022).